CD59 (CD59 molecule (CD59 blood group))
Diseases named in the same sentence as CD59 in open-access papers (continued):
Sharing a sentence is not in itself a finding about the gene and the disease.
cancer (82 papers, 1993 to 2025). A tumor composed of atypical neoplastic, often pleomorphic cells that invade other tissues. "Using a variety of analysis methods, we identified the genomic and functional networks associated with the expression of CD59 in human cancers." (PMID 39518137, 2024). "We observed similar correlations in CESC, GBM, HNSC, and STAD cancers, where a strong association between CD59 and TAM is linked to worse prognosis through IL10/STAT3-dependent pathways." (PMID 39518137, 2024). "Elevated CD59 levels are associated with a worse prognosis in several cancers, including colorectal, prostatic, ovarian, and lung cancers." (PMID 39518137, 2024). "Multispecific antibodies targeting TAMs, CD59, IL-6 and targetable cancer mutations might be a new promising strategy for cancer immunotherapy." (PMID 31685825, 2019). "ARF6 has been associated with several cell-surface receptors expressed on cancer cells, such as CD147, CD44, CD98, CD55, and CD59." (PMID 40733075, 2025). "Cancer cells upregulate the expression of CD55/CD59 through the EGFR/Wnt/β-catenin pathway, which results in the inhibition of the complement system and cytokine secretion." (PMID 39958348, 2025). "Through the mechanism of promoter occupancy, it increases CD59, thereby enhancing cancer cells resistance to complement-dependent cytotoxicity (CDC)." (PMID 39958348, 2025). "Given the importance of its immunomodulatory role, there is significant therapeutic potential for targeting CD59 in the treatment of cancers and infectious diseases." (PMID 40272315, 2025). "The analysis was performed for five cancers with high CD59 expression using the TCGA database from GEPEA 2, focusing on overall survival (OS)." (PMID 39518137, 2024). "To assess CD59’s role in the Treg population within cancers, we performed a correlation analysis between CD59 and Tregs across various cancers." (PMID 39518137, 2024). "This study focuses on cancers with elevated CD59 mRNA and protein expression, analyzing the correlation between CD59 levels and survival outcomes." (PMID 39518137, 2024). "The GEPIA database provides a comparison of CD59 transcriptional levels in a variety of TCGA cancer samples with normal samples." (PMID 39518137, 2024). "This aspect warrants investigation to better understand how CD59 modulates the immune response in different cancers." (PMID 39518137, 2024). "Overall, through a comprehensive analysis of CD59 expression across various cancers, we systematically evaluated its prognostic significance and its relationship with immune cells." (PMID 39518137, 2024). "Despite these insights, the study mainly relies on publicly available databases, highlighting the need for additional animal research to elucidate the role of CD59 and its interactions with immune cells in cancer." (PMID 39518137, 2024). "CD59 is widely expressed, and its expression levels are higher in the majority of cancer cells than in adjacent normal cells." (PMID 39518137, 2024). "To explore similar mechanisms in other cancers, we conducted a correlation analysis of CD59 with macrophage, IL10, IL10RB, IL6, and IL6R on KIRC, CESC, GBM, HNSC, and STAD." (PMID 39518137, 2024). "Our results indicate that elevated CD59 levels in many cancers contribute to the inhibition of MAC-mediated cytotoxicity, correlating with poor outcome; however, KIRC has the opposite trend with favorable outcomes." (PMID 39518137, 2024). "The resulting DOX-loaded MIPs (MIPs@DOX) exhibited a specific targeting ability for CD59-overexpressing MCF7 cancer cells with FI-guided target imaging." (PMID 37173721, 2023). "Protein alterations similarly described in other malignancies include reduced levels of CD59 in AML35 and cancer-promoting loss of fumarate hydratase (FH) in a variety of cancers." (PMID 37828014, 2023). "The top five ligands targeting CD8+ T-cells by mesenchymal cancer cells from infiltrated tumors were HLA-C, HLA-A, CD59, LGALS3, and B2M." (PMID 38086828, 2023).
cancer (continued). "Low expression of terminal elements (C8A, C8B, and C9) was detected in all cancer types, whereas complement regulators (C1inh, FH, FI CD46, CD55, and CD59) are highly expressed in most cancers." (PMID 38003705, 2023). "In a paper reviewing expression of complement in various cancers most cancers over-expressed C3 but neutrally-expressed C5, and the most over expressed gene was CD59, suggesting efficient protection of malignant cells from complement-mediated killing." (PMID 37034706, 2023). "These FZIF-8/DOX-MIPs not only targeted tumors that overexpressed CD59 glycoproteins, but also allowed for both the in vitro and in vivo CD-based fluorescence imaging of cancer cells." (PMID 37173721, 2023). "Comparative transcriptome analysis using The Cancer Genome Atlas (TCGA) data revealed a positive correlation between the NANOG signature and CD59 mRNA levels in multiple human cancer types." (PMID 35606403, 2022). "Inhibition of complement activation via the overexpression of complement-regulatory proteins (CRPs), most notably CD46, CD55 and CD59, is an efficient mechanism of disguise of cancer cells from a host immune system." (PMID 35563599, 2022). "While treatment of cancer cells with cetuximab caused the downregulation of CD46 and CD59, the overexpression of CD46 protected the cells not only from direct effects via ADCC and CDC but also through indirect effects." (PMID 36575233, 2022). "The regulation of complement pathway was also enriched and the complement regulatory protein that protects epithelial cancer cells from complement attack, CD59 glycoprotein (protectin) was detected in cancer NAF samples." (PMID 34064148, 2021). "Unfortunately, our study also detected CD59 by Wes in the EVs from the non-cancer HOKg cell line, making this protein a less desirable candidate for progression in our studies." (PMID 34359613, 2021). "It is found that CD59 is necessary for the epithelial cancer stem cells to evade complement monitoring." (PMID 34322132, 2021). "In recent years, LAMTOR3 and CD59 have been extensively used to inhibit the development of a variety of cancers." (PMID 34803519, 2021). "It is not specific of GBM, however possible targeted therapies inhibiting CD59 are currently under investigation for other types of cancers." (PMID 33374813, 2020). "In general, downregulation of CD59 promotes the activation of complement‐mediated cell lysis while increased expression can confer resistance to cancer cells." (PMID 33718121, 2020). "Current evidence supports adjuvant use of CD-59 blockade in order to enhance efficacy of anti-cancer immune therapies." (PMID 33344222, 2020). "Incidentally, high expressions of CD46, CD55, and CD59 are homogenously expressed and positively correlate with increased metastatic tumor cells in the liver of patients with colorectal and other cancers with poor prognosis." (PMID 33718121, 2020). "The membrane complement inhibitor CD59 expression has been reported to be upregulated in many cancers including bladder and is correlated with cell proliferation, apoptosis and immune evasion." (PMID 32922663, 2020). "Regardless of the spectrum of expression, extreme variations in the levels of CD59 result in pathologic outcomes of oncogenesis or cancer progression." (PMID 33718121, 2020). "One research had shown that up-regulation of CD59 in cancer stem cells (CSCs) allowed it avoid complement attack, and silence of CD59 can completely eliminate tumors in a mouse model in which CSCs were implanted." (PMID 30636930, 2019). "CD59 is highly expressed on cancer cells to regulate complement activation and is highly associated with chemotherapy resistance and radio resistance." (PMID 31685825, 2019). "It is known that tissues and cell types can vary widely in CD59 expression and that many cancer cell types express increased levels of CD59." (PMID 29693588, 2018).
cancer (continued). "Experimental evidence has shown that CD59 is effective at protecting cancer cells from antibody (i.e., rituximab) mediated complement-dependent cytotoxicity." (PMID 28400759, 2017). "One possibility is that since the turnover of cancer cells bearing CD59 is low as they are generally "immortal", less of the cell surface molecules are being solubilized and excreted in the urine." (PMID 21083881, 2010). "The contrasting PMA-induced CD59 expression in PMNs and cancer cells suggests different responses by these cell types to PMA stimulation." (PMID 18578885, 2008). "Meanwhile, CD55 and CD46 on malignant cells restrict deposited C4b and C3b, and CD59 inhibits complement membrane attack complex formation, therein protecting cancer cells from membrane damage." (PMID 17623109, 2007). "Similarly, in human ovarian A2780 cancer cells, IL-6 stimulates CD59 expression at low concentrations, but at high concentrations or with IL-8, it presents a post-transcriptional inhibitory effect." (PMID 40370471, 2025). "Overall, CD59 shows high mRNA expression in 14 out of 29 different cancer types." (PMID 39518137, 2024). "Thus, our findings reveal new insight into CD59 and its immune interactions, which can be utilized for human cancer diagnosis, prognosis, and treatment." (PMID 39518137, 2024). "We further analyzed the correlation between CD59 and MDSCs in these cancers." (PMID 39518137, 2024). "However, the expression of CD59 in human cancer and its impact on prognosis and targeted therapy remains under-explored." (PMID 39518137, 2024). "Repressing the terminal lysis capacity of the complement system through the involvement of the inhibiting RCA protein CD59 is characteristic of cancer resistance and of the action of infectious pathogens, which tend to hijack the complement system regulators to defend from its aggression." (PMID 37239905, 2023). "CD59 is also overexpressed in several cancer cells to resist the complement attack." (PMID 37239905, 2023). "CD59, a complement regulatory protein that downregulates complement-mediated cell lysis, could mediate immune regulation and produce resistance to cancer cells." (PMID 36294966, 2022). "However, previous studies have reported a significant downregulation of membrane-bound complement regulators (CD46, CD55, and CD59) in SCLC compared to other cancers, including NSCLC." (PMID 34996345, 2022). "Knockdown of NANOG resulted in decreased expression of CD59 in the indicated cancer cells." (PMID 35606403, 2022). "Alterations in CD59 always followed induction of tumorigenesis or cancer progression." (PMID 36294966, 2022). "Current reports have revealed high expression of CD59 in various cell lines and tissues of cancer." (PMID 34322132, 2021). "The CD59 antibody will recognize the corresponding receptor overexpressed in the cancer cells that promote the enhanced internalization of CD/LP-miCDDP in the cancer cells." (PMID 32185543, 2020). "Moreover, the membrane-bound complement regulatory proteins (mCRPs), including MCP (CD46), DAF (CD55), and CD59, have been found overexpression in many cancer cells." (PMID 33614473, 2020). "It has been hypothesized that cancer cells escape from complement system by activating complement inhibitors, such as CD59, CD46, and CD55." (PMID 32922663, 2020). "It is worth stating that the CD59 expression levels of different types of cancer cells vary." (PMID 31685825, 2019). "In addition, the expression of membrane-bound complement regulatory proteins (mCRPs), including CD46, CD55 and CD59, is upregulated in many types of cancer cells, which can dwarf antitumor therapeutic efficacy." (PMID 31787848, 2019). "In addition, the targeting of mCRPs, such as CD46 and CD59, for cancer immunotherapy has recently been explored." (PMID 31787848, 2019). "Again, prostasomes from cancer cells express higher CD59 levels than those from normal cells." (PMID 24707491, 2014).
cancer (continued). "However, previous studies have shown that PMA and PKC activity enhanced CD59 expression in cancer cells and therefore, increased the survival of these cells." (PMID 18578885, 2008). "Should the complement cascade override the effects of CD55 (and CD46, another mCRP) and manage to activate the terminal complement components on cancer cell membranes, functional CD59 molecules bind to human C8 and C9, during the attempt to properly assemble the membrane attack complex." (PMID 17623109, 2007). "In addition, carcinomas without metastases at the time of operation (Dukes A/B) more often expressed CD59 in the entire neoplastic population compared to those carcinomas which had already metastasised (P = 0.018)." (PMID 7692919, 1993). "Besides underlining the importance of neutralizing the mCRPs activity, the use of bispecific antibodies appears advantageous in this setting as they selectively address cancer cells and avoid the on-target, off-tumor attacks due to widely distributed CD59 expression." (PMID 35563599, 2022). "Thus, CD59 is a promising new target for cancer immunotherapy." (PMID 31413735, 2019). "It has been reported that CD46, CD55 and CD59 could protect cancer cells from MAC-mediated CDC." (PMID 31787848, 2019). "Combined therapy by targeting TAMs, CD59 and IL-6 may be a direction for cancer treatments." (PMID 31685825, 2019). "Additionally, several different complement-regulatory proteins (CRPs) function to inhibit complement activation, and certain membrane-bound CRPs such as CD46, CD55, and CD59 were reported to be aberrantly expressed in various cancers, which likely confers resistance to CDC." (PMID 29354121, 2017). "Cancer prostasomes also may inhibit complement through an alternative mechanism: by expressing CD59, a glycosylphosphatidylinositol-anchored protein that prevents the full assembly of the membrane-attack complex of complements, they inhibit complement-mediated lysis." (PMID 24707491, 2014). "Complement regulatory proteins, CD55, CD59, MCP, CD46, FH, and FH-like proteins are often upregulated in cancers with variations among cancer types and tumor specimens of the same cancer type." (PMID 40309765, 2025). "In TGFβ-dominant cancers like CESC, GBM, HNSC, and STAD, MDSCs are positively correlated with CD59, contributing to increased immune suppression." (PMID 39518137, 2024). "Immunologically quiet cancer such as KIRC, where CD59 has less interaction with immune suppressive cells such as Treg, MDSC, and TAM, predicts favorable outcomes." (PMID 39518137, 2024). "As the CD59/CD55‐deficient phenotype is measured in the human erythrocyte PIG‐A assay, it might be hypothesized that cisplatin‐induced GPI‐deficient PIG‐A mutant erythrocytes in cancer patients are under pressure for elimination by the complement system, as occurs in PNH patients." (PMID 38214136, 2024). "Consistent with its importance as a therapeutical target, CD59-targeting antibodies have been proven to be successful in hindering HIV-1 growth and counteracting the effect of complement inhibition by specific cancer cells." (PMID 37239905, 2023). "In this context, we are also the first to explore the clinical significance of plasma EV levels of CD59 and TSPAN9 in cancer." (PMID 36612172, 2022). "Adjuvant cancer therapy is utilizing monoclonal antibodies (mAbs) directed against complement regulatory proteins (CRPs), including CD46, CD55, and CD59." (PMID 36294966, 2022). "Membrane-bound CRPs such as CD55 (DAF) and CD59 (MSK21) are known to inhibit complement activity and are often upregulated in cancer, with some prognostic capacity in HER2+ BC patients." (PMID 35167491, 2022). "CD59, a GPI-anchored membrane protein, inhibits the development of the membrane attack complex, preventing complement activation and perhaps protecting cancer cells from complement-dependent cytotoxicity." (PMID 36612172, 2022).
cancer (continued). "In this study, cetuximab inhibited the expression of CD46 and CD59, but stimulated that of CD55, thereby protecting cancer cells from both CDC and ADCC." (PMID 36575233, 2022). "The markers CALML5, CD59, and LIMA1 were chosen based on their promising prognostic value presented in the Pathology Atlas and their perceived cancer cell specificity, as well as the availability of validated antibodies." (PMID 34069237, 2021). "Some of the APA targets are surface receptors with well-known involvement in cancers (CD44, CD47, and CD59)." (PMID 34521731, 2021). "For instance, CD-55 and CD-59 are crucial complement regulatory proteins elevated in various cancers, while Carcino-embryonic antigen (CEA) is a highly specific cancer biomarker, whose targeted immunotherapies are still in the early clinical trials." (PMID 33344222, 2020). "Cancer cells are known to express, and sometimes overexpress, the membrane complement inhibitor proteins CD46, CD55, and CD59." (PMID 33126570, 2020). "The strongest overexpressed proteins in treated Caco-2 exosomes (eg, CD59, CRP, CTSD, HMMR, TRIM22) are involved as potential oncogenes in the pathogenesis of different cancers, including CRC." (PMID 25594007, 2014). "Cancer cells, in particular, possess membrane complement regulatory proteins (mCRPs such as CD46, CD55 and CD59) on their surfaces to ultimately thwart MAC pore formation and only allow for about 50%–60% cancer cell kill rates in vitro." (PMID 24276022, 2013). "Blocking CD59 inhibitory function with monoclonal antibody revealed that CD59 played a key role in protecting unsynchronized Bcap37 and MCF7 cancer cells from the complement membrane attack complex." (PMID 17623109, 2007). "Therefore, hypothetically, in a scenario where SSEA-4-positive PCa cancer cells are resistant to docetaxel treatment, CD95 and CD59 will be dysregulated as well." (PMID 39162992, 2025). "In addition, TGFβ1-dominant cancers such as CESC, GBM, and HNSC showed a high correlation between CD59 and TGFβ1, leading to suppression of cytotoxic T cell activity." (PMID 39518137, 2024). "The role of CD59 in cancer growth and interactions between CD59 and immune cells that modulate immune evasion has not been well explored." (PMID 39518137, 2024). "Correlation analysis of CD59 and TGFβ shows a positive correlation in these cancers, but not in KIRC." (PMID 39518137, 2024). "We found cancer stem cell gene, CD24 (logFC = 0.9), and therapy resistant genes, CD46 (logFC = 0.3) and CD55 (logFC = 0.4) expressed in ES1, ES2, and ES3 combined, compared to ES0, and cancer stem cell marker, CD59 to be the highest in ES1 (logFC = 0.4)." (PMID 38328306, 2023). "Moreover, the expressions of CD59, C3aR, and C5aR colocalized with PTX3 in MUC1H cancer tissue (respectively)." (PMID 36902242, 2023). "Removal of GPI-anchored proteins, which include the complement-regulatory proteins CD59 and CD55 but not CD46, with PI-PLC treatment resulted in enhanced susceptibility of cancer cells to complement lysis." (PMID 35227072, 2022). "The single genes CD59, RAP80 and SOX17 have been reported to serve as DNA-repair-related biomarkers to predict patients’ prognosis in ESCA or subtypes of this cancer." (PMID 34257547, 2021). "Furthermore, published cancer surface markers CD44 and CD59, as well as the insulin-like growth factor binding protein 2 (IGFBP2), were expressed in all analyzed CSCs." (PMID 33800955, 2021). "In this context, Chen and Ding demonstrated gradually increased CD59 expression levels in different breast- and lung parental cancer cell lines and further observed that the absence of CD59 resulted in a completely suppression of tumorigenesis in vivo." (PMID 33800955, 2021). "CD59 is a GPI-anchored membrane protein that prevents complement activation by inhibiting the formation of the membrane attack complex, which may protect cancer cells from complement-dependent cytotoxicity (CDC)." (PMID 31685825, 2019).